ENSG00000285528 (novel protein)
Gene: Protein-coding gene on chromosome 12 (56,449,700 to 56,488,170, reverse strand). Ensembl gene ENSG00000285528.
Genetic constraint (gnomAD): Missense variants: 86 observed, 68.29 expected, observed/expected ratio (o/e) 1.26, 90% interval 1.06 to 1.51. Synonymous variants: 33 observed, 27.06 expected, observed/expected ratio (o/e) 1.22, 90% interval 0.92 to 1.63.